GAB1 (GRB2 associated binding protein 1)
Diseases named in the same sentence as GAB1 in open-access papers (continued):
Sharing a sentence is not in itself a finding about the gene and the disease.
asthma (2 papers, 2013 to 2023). "Only one study reported that the LD block region including rs1397527 contained the GAB1 gene and was locus susceptible to asthma in adults." (PMID 38057792, 2023). "A study targeting childhood asthma in Europeans found that the variant of the GAB1 rs3805236 was associated with susceptibility to childhood asthma." (PMID 38057792, 2023). "According to the currently reported genome-wide association studies (GWAS), the LD block region including rs1397527 and containing the USP38/GAB1 genes has been identified as a susceptibility locus for adult asthma in the Japanese population." (PMID 38057792, 2023). "Quite recently, a genome-wide association study conducted by Tamari's group identified Gab1 as a candidate gene for adult asthma in the Japanese population." (PMID 23431498, 2013). "Therefore, we used the technique of an improved multiplex ligation detection reaction to sequence GAB1 gene and investigated the involvement of Single-nucleotide variants (SNVs) in GAB1 gene in asthma and ICS efficacy in asthmatic children." (PMID 38057792, 2023). "Recent research has reported that GRB2 associated binding protein 1 (GAB1) gene may participate in the pathogenesis of asthma by regulating the NF-κB pathway." (PMID 38057792, 2023). "Recent studies have confirmed that the expression of the GRB2 associated binding protein 1 (GAB1) gene may be related to the pathogenesis of asthma." (PMID 38057792, 2023). "In this study, the rs1397527 locus of the GAB1 gene was associated with EOS and ICS efficacy and was more strongly associated with asthma than the other loci." (PMID 38057792, 2023). "Collectively, this study analysed the genetic variant of the GAB1 gene and found that no SNVs were individually associated with asthma susceptibility, but when analyzing haplotypes of variants located in GAB1 gene there were positive results that haplotype AGGAGC was a risk factor for asthma." (PMID 38057792, 2023). "Therefore, we speculate that GAB1 is a response gene for GC therapy of asthma." (PMID 38057792, 2023). "Therefore, GAB1 may be involved in the pathogenesis of asthma." (PMID 38057792, 2023).
B-cell lymphoma (2 papers, 2013 to 2020). "miR-150 has been confirmed to target Grb2-associated binder 1 (GAB1) and Foxp1 in normal B cells and several B-cell lymphomas." (PMID 33194698, 2020). "• Len inhibited proliferation of B-cell lymphoma cells and interfered with Gab1 phosphorylation and adaptor protein complex assembly." (PMID 23915913, 2013).
cervical cancer (2 papers, 2022 to 2023). A primary or metastatic malignant neoplasm involving the cervix. "The absence of protein tyrosine kinase 6 (PTK6) expression reduces the proliferative capacity of cervical cancer cells and apoptosis induction in a GAB1-dependent manner." (PMID 37627207, 2023). "Overexpression of GAB1 was able to offset the inhibitory effects of PTK6 knockdown on cervical cancer cells." (PMID 36405012, 2022). "For instance, it was observed that the expression levels of PTK6 and GAB1 were much higher in cervical cancer cell lines compared to those noted in normal cervical epithelial cells." (PMID 36405012, 2022). "GAB1 overexpression increases migratory and invasive activity in cervical cancer cell lines." (PMID 37627207, 2023).
chronic lymphocytic leukemia (2 papers, 2016 to 2023). "Likewise, GAB1 has been found to increase the migration of chronic lymphocytic leukemia cells by forkhead box 1 (FOXO1) regulation." (PMID 37627207, 2023). "Furthermore, it has been reported that chronic lymphocytic leukemia (CLL) cells treated with ibrutinib lead to an increase in GAB1 mRNA and protein levels." (PMID 37627207, 2023). "Recently, Mraz's group found that the expression of GAB1 and FOXP1 is modulated by miR-150, resulting in proficient B-cell receptor signaling in chronic lymphocytic leukemia, which is consistent with our findings." (PMID 26871477, 2016).
congenital heart disease (2 papers, 2015 to 2023). A heart disease that is present at birth. "It would be interesting to see how Gab1 expression levels would be following corrective surgery for cyanotic congenital heart disease." (PMID 26090437, 2015). "Here we showed that Gab1 is expressed in myocardial tissue in acyanotic and cyanotic children with congenital heart defects." (PMID 26090437, 2015). "The expression of GAB1, a gene involved in PI3K/Akt signaling, was found to be reduced in the fetal heart tissue of diabetic rats, contributing to an increased risk of congenital heart defects." (PMID 37571325, 2023).
glioblastoma (2 papers, 2018 to 2023). The most malignant astrocytic tumor (WHO grade IV). "Also, GAB1 has been reported to be closely involved in glioblastoma cell invasion through HGF-induced activation of dedicator of cytokinesis 7 (DOCK7) and RAC1." (PMID 37627207, 2023). "GAB1 acts as a molecular switch that allows the interconnection of different cell signaling pathways such as the connection between the EGFR/PI3K/AKT pathway and the nuclear factor kappa-light-chain-enhancer of activated B cells (NF-kB) pathway in glioblastoma cells." (PMID 37627207, 2023).
heart failure (2 papers, 2021 to 2023). Inability of the heart to pump blood at an adequate rate to meet tissue metabolic requirements. "In addition, cardiac Gab1 deletion leads to heart failure in aged mice associated with cardiomyocytes’ apoptosis, in which apoptosis is considered immunologically silent and restricts the spread of inflammation." (PMID 36795486, 2023). "Cardiac Gab1 deletion leads to cardiomyocyte apoptosis and heart failure while hepatocyte Gab1 controls the balance between acetaminophen-induced hepatocyte death and compensatory proliferation." (PMID 36795486, 2023). "Cardiac-specific Gab1 knockout mice rapidly developed severe DCM and heart failure after the onset of cardiac hemodynamic stress, furthermore, gene microarray analysis revealed the upregulation of several pro-apoptotic genes and downregulation of some key anti-apoptotic genes." (PMID 35118147, 2021).
multiple sclerosis (2 papers, 2020). A progressive autoimmune disorder affecting the central nervous system resulting in demyelination. "Considering its unique expression, the roles of Gab1 in axonal remyelination and its therapeutic implications for demyelinating diseases such as multiple sclerosis, in which adult OPCs fail to differentiate effectively, might be expected." (PMID 31944179, 2020).
non-small cell lung carcinoma (2 papers, 2021 to 2023). A group of at least three distinct histological types of lung cancer, including non-small cell squamous cell carcinoma, adenocarcinoma, and large cell carcinoma. "GAB1 has been described to be involved in alectinib resistance mediated by activation of the HGF/MET signaling pathway in anaplastic lymphoma kinase (ALK)-positive non-small cell lung cancer." (PMID 37627207, 2023). "Also, eukaryotic translation initiation factor 4 gamma 2 (EIF4G2)–GAB1 fusion has been found in patients with non-small cell lung cancer treated with EGFR TKI." (PMID 37627207, 2023).
Obesity (2 papers, 2022 to 2023). Accumulation of substantial excess body fat. "DNA methylation change of 15 imprinted genes induced by HFD feeding was observed, including Magel2, Ctnna3, Gab1, and L3mbtl1, that are reported to be linked to the pathogenesis of obesity, high cognitive processes in adulthood, circadian machinery, and growth and development of embryos." (PMID 35458198, 2022).
renal carcinoma (2 papers, 2010 to 2022). A carcinoma arising from the epithelium of the renal parenchyma or the renal pelvis. "GAB1 is prognostic, and high expression of GAB1 is beneficial to the survival of patients with renal cancer (The Human Protein Atlas), thus revealing that the expression of GAB1 is low in renal cancer." (PMID 36789694, 2022).
adult onset asthma (1 paper, 2020). "A singular GWAS study of a Japanese adult-onset asthma population showed that SNPs of HLA-, thymic stromal lymphopoietin-WD repeat domain 36 (TSLP-WDR36)-, and ubiquitin specific peptidase 38-GRB2 associated binding protein 1 (USP38-GAB1) loci are associated with adult-onset asthma." (PMID 32292784, 2020).
allergic asthma (1 paper, 2023). A asthma with a basis in a pathological type I hypersensitivity reaction. "They observed an elevation of GAB1 level in peripheral blood mononuclear cells from asthmatic patients during acute exacerbation, and further experiments found that GAB1 can regulate DC migration in allergic asthma by affecting CCL19/CCR7 signaling." (PMID 38057792, 2023).
Alzheimer disease (1 paper, 2016). A progressive, neurodegenerative disease characterized by loss of function and death of nerve cells in several areas of the brain leading to loss of cognitive function such as memory and language. "With their innate physiological roles as well as being direct interacting partners (guilt-by-association) to already known AD genes (JAK2 and PECAM1) increases the chances of the two genes (CSF1R and GAB1) as novel candidate genes for Alzheimer’s disease." (PMID 26784894, 2016). "Our network analysis provided sufficient arguments in favor of GAB1 as novel candidate genes for Alzheimer’s disease based on its direct network interactions with already known AD genes." (PMID 26784894, 2016).
bladder cancer (1 paper, 2016). "Differentially expressed genes involved in ErbB signalling pathway pointed strong alterations of GAB1 and AREG in the bladder cancer tissues." (PMID 27779188, 2016).
bladder tumor (1 paper, 2015). "As expected, immunohistochemical staining showed significantly increased expression of Gab1, phosphorylation of mTOR at Ser2481 and phosphorylation of AKT at Ser473 in both human and rat bladder tumor tissues but not in normal bladder tissues." (PMID 25596749, 2015).
breast tumors (1 paper, 2021). "In opposition with our findings, GAB1 was found up-regulated in breast tumors compared to benign mammary hyperplasia from patients." (PMID 34681793, 2021).
cardiac hypertrophy (1 paper, 2021). "The Grb2-associated binder 1 (Gab1), a key mediator of growth factor receptor signaling, also participated in the regulation of cardiac hypertrophy induced by pressure overload." (PMID 35118147, 2021).
Chronic colitis (1 paper, 2023). A chronic inflammatory disease of the large intestine (colon, cecum and rectum). "Chronic colitis is considered a high risk factor for CRC; therefore, we extended our studies to investigate the role for Gab1 in CAC and CRC." (PMID 36795486, 2023). "Gab1IEC-KO mice exhibited increased number and size of tumors in the colorectum compared with Gab1fl/fl mice, suggesting a protective role for Gab1 in tumorigenesis driven by chronic colitis in mice, which is consistent with our bioinformatic results in patients with CRC." (PMID 36795486, 2023).
chronic liver failure (1 paper, 2021). Liver failure that develops slowly and gradually for some time, possibly for years, often as the result of cirrhosis, or malnutrition. "The expression levels of Gab1, TPO, and c-Mpl mRNA in the liver tissues of rats with chronic liver failure were significantly lower than those observed in the blank group (P < 0.05)." (PMID 33959189, 2021).
colon adenocarcinoma (1 paper, 2023). "Therefore, we analyzed the CRC database and found a significant decrease of Gab1 expression in both patients with colon adenocarcinoma (COAD) and patients with rectal adenocarcinoma (READ) compared with healthy controls." (PMID 36795486, 2023).
Cyanosis (1 paper, 2015). Bluish discoloration of the skin and mucosa due to poor circulation or inadequate oxygenation of arterial or capillary blood. "In this study, we investigated the effects of cyanosis on Gab1 in myocardium samples from paediatric patients suffering from TOF and we examined the effects of hypoxia in primary cultures of rat neonatal cardiomyocytes on Gab1 and its possible role in cell survival." (PMID 26090437, 2015).
esophageal cancer (1 paper, 2021). A primary or metastatic malignant neoplasm involving the esophagus. "KYSE520, an EGFR-amplified esophageal cancer cell line, showed loss of GAB1 Y659 phosphorylation with SHP099 treatment under conditions of EGF stimulation." (PMID 33755016, 2021).
fibrosis (1 paper, 2021). the formation of excess fibrous connective tissue in an organ or tissue in a reparative or reactive process. "Indeed, during bleomycin-induced experimental fibrosis, IL-4-induced macrophage polarization is modulated by Grb2 associated binding protein 1 (Gab1) and Gab2." (PMID 33670759, 2021).
gestational diabetes (1 paper, 2025). Carbohydrate intolerance first diagnosed during pregnancy. "Furthermore, dysregulated expressions of several imprinted genes (e.g., Igf2, Phlda2, H19 and Gab1) in the placenta have been implicated in various pregnancy complications, including preeclampsia, gestational diabetes and FGR." (PMID 40550626, 2025). "Dysregulation of imprinted genes, including Igf2, Phlda2, H19 and Gab1 has been observed in placentas affected by pregnancy complications including preeclampsia, gestational diabetes and FGR." (PMID 40550626, 2025).
HCMV infection (1 paper, 2020). "Thus, by simply fine-tuning GAB1 protein levels during HCMV infection, miR-US5-2 can significantly modulate signal transduction through multiple cellular signaling pathways." (PMID 32759334, 2020). "Expression of a NAB1 shRNA in the context of HCMV infection does not significantly affect UL138 expression compared to the parental ΔmiR-US5-2 virus, indicating that miR-US5-2 targeting of GAB1, and not NAB1, mediates the effect of the miRNA on UL138 protein levels." (PMID 32759334, 2020).
head and neck cancer (1 paper, 2023). A primary or metastatic malignant neoplasm affecting the head and neck. "Additionally, it has been described that decreased GAB1 expression levels in head and neck cancer cell lines (HN4, HN6, HN12, HN13, and HN31) increased sensitivity to the EGFR inhibitor gefitinib by decreasing MAPK and AKT phosphorylation." (PMID 37627207, 2023).
influenza infection (1 paper, 2025). "Gab1 knockdown in vivo, or LY294002 (a PI3K inhibitor), abolishes the PROS1/AXL-induced protective activity against lethal influenza infection in mice." (PMID 41158072, 2025).
keloid (1 paper, 2021). An irregularly shaped, elevated mark on the skin caused by deposits of excessive amounts of collagen during wound healing. "Importantly, miR-141-3p suppresses fibroblast proliferation and migration via targeting GAB1 in keloids." (PMID 33977869, 2021).
latent infection (1 paper, 2020). "Expression of miR-US5-2 and targeting of GAB1 may represent means to limit the extracellular signaling that promotes entry into the cell cycle during lytic and latent infection." (PMID 32759334, 2020).
leukaemia (1 paper, 2019). "For example, the uncontrolled proliferation of Jak2-V617F positive leukaemia cells might thus be explained by malregulated Gab1 and constitutive activation of Erk1/2 as observed in Jak2-V617F-positve cells." (PMID 31651330, 2019). "Therefore, it is worth to investigate whether Gab1 expression levels correlate with progression of other solid tumour types or leukaemia in detail." (PMID 31651330, 2019).
lung adenocarcinoma (1 paper, 2015). A carcinoma that arises from the lung and is characterized by the presence of malignant glandular epithelial cells. "Under these circumstances, our data suggest that the Gab1-Shp2 pathway is activated in these EGFR inhibitor-resistant lung adenocarcinoma cells and promotes tumor growth." (PMID 25730908, 2015). "Constitutive Gab1-Shp2 binding in human lung adenocarcinoma cells harboring mutant EGFR was observed in a previous study and in this study." (PMID 25730908, 2015). "Consistently, the Gab1-Shp2 pathway was activated in human lung adenocarcinoma cells containing mutant EGFR." (PMID 25730908, 2015). "In HCC827 and H1975 human lung adenocarcinoma cells that harbor mutant EGFR (del19 and L858R/T790M mutations, respectively), Gab1 was constitutively tyrosine phosphorylated and bound Shp2." (PMID 25730908, 2015). "To further confirm that Shp2, Gab1-Shp2 interaction, and Shp2 PTP activity mediate Erk1/2 activation in lung adenocarcinoma cells that harbor mutant EGFR, we compared the pErk1/2 level in isogenic HCC827 cells containing two different Dox-inducible Shp2 shRNAs." (PMID 25730908, 2015). "Using Shp2 siRNAs, Dox-inducible shRNAs, Shp2 binding defective Gab1 mutant, and PTP-inactive Shp2 mutant, we have provided evidence that inhibition of Gab1-Shp2 interaction and Shp2 PTP activity suppress Erk1/2 activation in the HCC827 lung adenocarcinoma cells that harbor a mutant EGFR." (PMID 25730908, 2015).
multiple myeloma (1 paper, 2023). "HCK-mediated phosphorylation of GAB1 induces proliferation and survival in IL-6-induced multiple myeloma cells." (PMID 37627207, 2023). "In addition to other resistance mechanisms, using GAB1 and SHP2-GAB1 binding mutants, GAB1 has been shown to be associated with the IL-6-induced dexamethasone resistance mechanism in multiple myeloma cells." (PMID 37627207, 2023). "Similarly, hematopoietic cell kinase (HCK) has been reported to induce GAB1 phosphorylation in response to IL-6 in multiple myeloma cells." (PMID 37627207, 2023).
osteoporosis (1 paper, 2025). A condition of reduced bone mass, with decreased cortical thickness and a decrease in the number and size of the trabeculae of cancellous bone (but normal chemical composition), resulting in increased fracture incidence. "The identification of ESR1, NRP2, AXL, ERBB2, and GAB1 as key genes provides novel therapeutic targets and highlights the importance of understanding shared molecular pathways in osteoporosis and sarcopenia." (PMID 40660573, 2025). "The 5 genes (AXL, GAB1, ERBB2, NRP2, and ESR1) along with 13 pharmacological agents represent promising candidates for enhancing the treatment of osteoporosis and sarcopenia." (PMID 40660573, 2025).
reovirus infection (1 paper, 2015). "First, we examined the phosphorylation of FAK and Gab1 in reovirus infection." (PMID 26388843, 2015).
schizophrenia (1 paper, 2022). A major psychotic disorder characterized by abnormalities in the perception or expression of reality. "Furthermore, genes (including GRM1, ADK, CACNA1C, CRK and GAB1) which the most significant SNPs of the five first-generation antipsychotics specific analyses are located within were both associated with the schizophrenia and heart diseases." (PMID 35136033, 2022).
systemic sclerosis (1 paper, 2021). A chronic disorder, possibly autoimmune, marked by excessive production of collagen which results in hardening and thickening of body tissues. "GAB1 facilitated the inflammation and fibrosis in systemic sclerosis." (PMID 33393621, 2021).
thyroid tumor (1 paper, 2019). A benign or malignant neoplasm affecting the thyroid gland. "In addition, it has been recently shown that Gab1-Erk1/2 and Gab1/PI3K/Akt pathway act as main downstream of Gab1 to regulate cancer proliferation and metastasis in thyroid tumors and HCC." (PMID 30665442, 2019).